IL17RB (interleukin 17 receptor B)
Diseases named in the same sentence as IL17RB in open-access papers (continued):
Sharing a sentence is not in itself a finding about the gene and the disease.
asthma (continued). "Moreover, the precise functions of METTL14, ALKBH5, and m6A methylation of IL17RB mRNA and lncRNAs in asthma need to be further elucidated." (PMID 36250525, 2022). "Moreover, we demonstrated that IL17RB mRNA level in lung in the asthma group was also higher than that of the control group." (PMID 36250525, 2022). "Together with other lung resident cells expressing IL-17RB, it is believed that IL-25 is highly contributed to the inflammation and lung damage via its direct action on lung endothelial cells, antigen presenting cells and Th2-related immune cells during asthma progression." (PMID 39717777, 2024). "In addition, IL-17RB +-CFs were correlated with FEV1/FVC in patients with asthma." (PMID 37635231, 2023). "This indicates that IL-17RB +-CFs may be a disease marker for asthma with FAL." (PMID 37635231, 2023). "This study showed that IL-17RB+ fibrocytes were increased in the blood circulation of asthmatic patients with FAL and in the lung tissues of chronic murine asthma models." (PMID 37635231, 2023). "An IL-17RB−/− mouse study demonstrated that decreases in Th2 cytokines and increases in Th17 cytokines reduced inflammation in mice with RSV-induced asthma exacerbation." (PMID 35008429, 2021). "Although distinct subsets of iNKT cells have been reported to be involved in different forms of asthma, they are now consolidated into CD4− and/or CD4+ IL-17RB+iNKT cell subsets." (PMID 22346732, 2012). "Therefore, the blockage of IL-17RB via SM17, a novel humanized monoclonal antibody, offers an attractive therapeutic target for Th2-mediated diseases, such as asthma." (PMID 39717777, 2024). "IL-17RB +-fibrocytes were also increased in the lung sections of chronic allergen- and non-allergen-induced mouse asthma models." (PMID 37635231, 2023). "Blocking of its receptor IL-17RB with SM17 may just offer inhibitory effects on these disease-contributing cytokines all at once, which could result in better restoration in normal lung histology and reduction in asthma exacerbations." (PMID 39717777, 2024). "Future studies should be conducted using a large asthma cohort to determine whether the percentage or number of IL-17RB+-CFs in the circulation can discriminate asthma patients with FAL from those without." (PMID 37635231, 2023).
pancreatic cancer (17 papers, 2016 to 2025). "Up-regulation of IL-17RB expression was also found in pancreatic cancer, where expression of IL-17RB associated with metastasis incidence and reduced progression free survival." (PMID 33244315, 2020). "In pancreatic cancer, high IL-17RB expression has been associated with postoperative metastases in patients." (PMID 32373132, 2020). "In solid tumors, amplified IL-17B/IL-17RB signaling is critical for breast and pancreatic tumorigenesis and elevated IL-17RB expression has been associated with the shortest survival rates in patients with breast or pancreatic cancer." (PMID 29371916, 2017). "Monoclonal antibodies against IL-17RB can block pancreatic cancer metastasis by silencing multiple chemokines and extending the lifespan of mice with pancreatic cancer." (PMID 39906741, 2024). "Studies on human prostate cancer tumor specimens revealed overexpression of IL-17RB and phosphorylated IL-17RB, playing a significant role in tumorigenesis and metastasis of pancreatic tumors." (PMID 39906741, 2024). "Meanwhile, in pancreatic cancer cells and tumor tissue, there is a positive correlation between the expression of IL-17RB and the expression of MUC1 and MUC4." (PMID 37686343, 2023). "PSCs with IL-17RB overexpression increased mitochondrial respiration and decreased glycolysis in pancreatic cancer cells, possibly acting as a modifier of cancer cell metabolism." (PMID 35370770, 2022). "PSCs overexpressing IL-17RB significantly promoted tumor formation of MiaPaCa-2 pancreatic cancer cells in immunodeficient mice by co-transplantation." (PMID 35370770, 2022). "It was also found that overexpression of IL-17RB was associated with metastasis and poor clinical outcome of pancreatic cancer, and impairing IL-17B-IL-17RB signaling blocked metastasis of pancreatic cancer." (PMID 36569325, 2022). "Interleukin-17B-containing exosomes were released from pancreatic cancer cells, which increased IL-17RB in PSCs." (PMID 35370770, 2022). "Pancreatic cancer cells and PSCs express interleukin-17B receptor (IL-17RB), and co-culture of pancreatic cancer cells and PSCs increased IL-17RB in PSCs." (PMID 35370770, 2022). "Exosomes from pancreatic cancer patients contained more IL-17B compared with healthy controls, suggesting that IL-17B-carrying EVs upregulate IL-17RB expression in PSCs." (PMID 34771503, 2021). "They subsequently confirmed that the metastatic ability of pancreatic cancer cells was significantly inhibited by blocking IL-17B/IL-17RB signaling with monoclonal antibodies that targeted IL-17RB." (PMID 33649532, 2021). "We performed co-culture of PSCs with pancreatic cancer cells and evaluated the IL-17RB expression on PSCs using immunoblots." (PMID 34771503, 2021). "To further confirm IL-17RB induction in PSCs, we investigated IL-17RB expression in human and murine PSCs with immunofluorescence microscopy after being treated with pancreatic cancer-derived conditioned medium (CM)." (PMID 34771503, 2021). "CM from IL-17RB KD PSCs (CM KD) increased the growth of pancreatic cancer cells to the same extent as CM from IL-17RB VEC KD PSCs (CM VEC KD)." (PMID 34771503, 2021). "Here we ask if PSCs interact with pancreatic cancer cells through Interleukin 17B/Interleukin 17B receptor (IL-17B/IL-17RB) cell-cell signaling." (PMID 34771503, 2021). "Through analysis of the individual cell compartments, we confirmed mitochondrial IL-17RB expression with Western blot in PSCs and pancreatic cancer cells." (PMID 34771503, 2021). "We injected human MIA PaCa-2 pancreatic carcinoma cells with control IL-17RB VEC OE PSCs respective IL-17RB OE PSCs into immunocompromised mice (NSG)." (PMID 34771503, 2021). "High IL-17RB expression was correlates with poor prognosis of pancreatic cancer, and targeting IL-17RB provides a therapeutic potential for pancreatic cancer treatment." (PMID 33082357, 2020).
pancreatic cancer (continued). "In our preliminary studies, overexpression of IL-17RB strongly correlated with post-operative metastasis and inversely correlated with progression-free survival in pancreatic cancer patients." (PMID 33082357, 2020). "Taken together, these results suggest that IL17B/IL-17RB signaling not only emerges as an important regulator of pancreatic cancer growth and metastasis, but is a feasible target for pancreatic cancer treatment." (PMID 33082357, 2020). "The present work demonstrates that activation of IL-17RB signaling confers pancreatic cancer cells with enhanced cancer stem-like property and resistance to gemcitabine treatment via enhanced MUC1 and MUC4 expression." (PMID 33082357, 2020). "Inhibition of IL-17RB by neutralization antibody D9 suppresses the cancer-stemness activity and enhances gemcitabine sensitivity in pancreatic cancer cells." (PMID 33082357, 2020). "Altogether, these findings provide feasible applications for IL-17RB-targeting therapy in pancreatic cancer treatment." (PMID 33082357, 2020). "Altogether, this study reveals attenuation of the stem-like property by targeting IL-17RB and provide a therapeutic strategy for pancreatic cancer treatment." (PMID 33082357, 2020). "Anti-IL-17RB neutralization antibody was reported to be capable of suppressing IL-17RB-mediated pancreatic tumor progression." (PMID 33082357, 2020). "Furthermore, IL-17RB has been identified as a potential prognostic marker and a predictor of the effectiveness of gemcitabine treatment in patients with resectable pancreatic cancer." (PMID 37686343, 2023). "Based on the IL-17RB induced metabolic changes in PSCs, we hypothesized that PSCs affect the metabolism of pancreatic cancer cells." (PMID 34771503, 2021). "We hypothesized that pancreatic cancer cells stimulate the upregulation of IL-17RB expression in PSCs through IL-17B." (PMID 34771503, 2021). "Indeed, treatment with IL-17RB-neutralizing antibody has a synergistic effect in combination with gemcitabine for killing pancreatic cancer cells." (PMID 33082357, 2020). "MUC1 and MUC4 are reported to be involved in stemness which confers drug resistance in cancer cells, implicating that overexpression of IL-17RB may lead to enhancement of chemotherapy resistance through upregulation of these genes in pancreatic cancer cells." (PMID 33082357, 2020). "Furthermore, it was observed that MUC1 and MUC4 are involved in IL-17RB-mediated resistance to gemcitabine in pancreatic cancer cells." (PMID 33082357, 2020). "Importantly, treatment with monoclonal antibody against the native form of IL-17RB delays the malignancy of pancreatic cancer cells expressing IL-17RB and significantly extends animal survival." (PMID 33082357, 2020). "Clinical findings of IL-17RB upregulation in PDAC patients as well as the positive correlation of IL-17 signaling blockade with tumor regression in mice provide additional support for the protumorigenic effect of IL-17 on pancreatic cancer prognosis." (PMID 32823814, 2020). "Anti-IL17RB monoclonal antibodies might impact metastatic pancreatic cancer, has it has been shown in a mouse model." (PMID 33244315, 2020). "Moreover, targeting IL-17RB is a feasible therapeutic strategy for pancreatic cancer." (PMID 33082357, 2020). "Furthermore, the size and number of the pancreatic tumor spheres were significantly reduced after anti-IL-17RB (D9) treatment, indicating that targeting-IL-17RB could inhibit cancer stemness activity." (PMID 33082357, 2020). "Thus, besides IL-17A, IL-17B also could play an important role in tumor progression through its binding to IL-17RB and might represent a potential therapeutic target in solid tumors, such as breast and pancreatic cancers." (PMID 29371916, 2017). "Previous studies have demonstrated high expression of IL-17RB in HCC and pancreatic cancer cells, as well as clinical tumor samples." (PMID 40630198, 2025).
pancreatic cancer (continued). "To examine the roles of MUC1 and MUC4 in IL-17RB-mediated stemness in the pancreatic cancer cells, we overexpressed FLAG-tagged IL-17RB, followed by knockdown of MUC1 and MUC4 by lentivirus-based shRNA in SU.86.86 cells." (PMID 33082357, 2020). "To evaluate the correlation between IL-17RB, MUC1 and MUC4, we examined the expression of these genes in a panel of human pancreatic cancer cell lines." (PMID 33082357, 2020). "Here we show interlukine-17 receptor B (IL-17RB) expression is positively correlated with MUC1 and MUC4 expression in pancreatic cancer cells and tumor tissue." (PMID 33082357, 2020). "Together, these results indicate IL17B/IL-17RB signaling is potentially involved in transcriptional regulation of MUC1 and MUC4 expression in pancreatic cancer cells." (PMID 33082357, 2020). "Conversely, IL-17RB or IL-17B knockdown in CFPAC-1 and BxPC3 pancreatic cancer cell reduces their soft agar colony formation in soft agar and cell invasion in vitro." (PMID 32373132, 2020). "Collectively, these results suggest IL-17RB could enhance gemcitabine resistance through upregulation of MUC1 and MUC4 in pancreatic cancer cells." (PMID 33082357, 2020). "It was observed that pancreatic cancer cells with higher IL-17RB expression (HPAF-II, BxPC3, Capan-2, and CFPAC-1) were more resistant to gemcitabine treatment, and were pancreatic cancer cells with lower IL-17RB level (SU.86.86 and MIA-PaCa2) are more sensitive to gemcitabine treatment." (PMID 33082357, 2020). "IL-17RB, MUC1, and MUC4 are mainly expressed on the surface membrane of pancreatic cancer cells." (PMID 33082357, 2020).
ovarian carcinoma (15 papers, 2015 to 2026). A malignant neoplasm originating from the surface ovarian epithelium. "In the present study, we discovered that the expression of IL-17RB in gastric CSCs was significantly higher than that in non-CSCs, which is similar to the finding of one study that the expression of IL-17RB was higher in CD133+ ovarian cancer CSCs than in A2780 cells." (PMID 33649532, 2021).
lung carcinoma (11 papers, 2019 to 2024). "Despite the potential role of the IL-17B/ILRB trial in lung cancer, microarray dataset analysis in a study was linked to IL-17B and IL-17RB gene expression indicating least patient survival." (PMID 34336101, 2021). "A previous study also reported that IL-17B treatment caused significant IL-17RB upregulation in lung cancer cells." (PMID 33649532, 2021). "In lung cancer, microarray dataset analysis also associated IL-17B and IL-17RB gene expression with poor patient survival." (PMID 32373132, 2020). "Interestingly, IL-17RB signaling through the ERK/GSK-3β/β-catenin pathway has been associated also with EMT in lung cancer." (PMID 32373132, 2020). "In lung cancer, ubiquitin ligase interleukin 17 receptor B (CRL4) and WD repeat domain 4 promotes the progression of lung cancer through ubiquitin degradation of the promyelocytic leukemia protein." (PMID 37675097, 2023). "At the same time, more and more evidences have proved that IL-17B/IL-17RB get trapped in the occurrence and poor prognosis of patients with malignant tumors such as pancreatic cancer, gastric cancer, lung cancer and breast cancer." (PMID 35392087, 2022). "Remarkably, IL-17RB providing signal across ERK/GSK-3β/β-catenin route is connected to lung cancer's EMT." (PMID 34336101, 2021). "Stimulation of the ERK/GSK-3β/β-catenin path after IL-17RB encouragement did promote the intrusion and relocation of human lung cancer cell lines—H441 and CL1-0, in in vitro studies." (PMID 34336101, 2021). "Upon IL-17RB knockdown in the lung cancer cell lines—A549 and CL1-5, the expression of Twist and Snail declined." (PMID 34336101, 2021). "In patients with lung cancer, IL-17RB expression level correlates with lymph node and distant metastasis occurrence." (PMID 32373132, 2020). "Specifically, in A549 an CL1-5 lung cancer cell lines that spontaneously expressed high level of IL-17RB, Snail and Twist expression was decreased upon IL-17RB knockdown." (PMID 32373132, 2020). "AKT/GSK-3β/β-catenin signaling pathway was promoted by IL-17B/IL-17RB signaling pathway to up-regulate Sox2, Oct4 and Nanog proteins, inducing stem cell transformation and epithelial to mesenchymal transformation of gastric cancer and lung cancer cells." (PMID 35392087, 2022). "Hence, in lung cancer, the level of expression of IL-17RB correlated significantly with distant metastasis and lymph nodes." (PMID 34336101, 2021). "Activation of the ERK/GSK-3β/β-catenin pathway following IL-17RB stimulation also promotes the invasion and the migration of H441 and CL1-0 human lung cancer cells in vitro." (PMID 32373132, 2020).
gastric cancer (10 papers, 2014 to 2025). A primary or metastatic malignant neoplasm involving the stomach. "The over-expression of IL-17RB is associated with poor prognosis and contributes to gastric cancer cells acquiring stemness." (PMID 39906741, 2024). "IL-17RB expression is significantly elevated in human gastric cancer tissue and is associated with poor prognosis, contributing to gastric cancer cells acquiring stemness." (PMID 39906741, 2024). "In the following study, we confirmed gastric cancer cells cannot autocrine IL-17B, and showed that increased levels of IL-17RB were associated with poor prognosis in gastric cancer patients." (PMID 27146881, 2016). "Here, we confirmed that the expression of IL-17RB in gastric cancer tissues was significantly increased, that overexpression was associated with poor prognosis of gastric cancer patients, and that overexpression was positively correlated with some stemness markers." (PMID 27146881, 2016). "In gastric cancer, the proliferation and migration of tumor cells can be promoted via the IL-17B/IL-17RB axis, which also upregulates cell stemness by triggering the AKT/β-catenin pathway." (PMID 37686343, 2023). "More recently, high IL-17RB expression was correlated with poor prognosis also in patients with gastric cancer, where the percentage of IL-17RB positive cancer cells is high in grade II to IV tumors and low in grade I tumors." (PMID 32373132, 2020). "IL-17RB expression in group 2 innate lymphoid cells (ILC2) is higher in peripheral blood mononuclear cells from patients with gastric cancer than in healthy donors." (PMID 32373132, 2020). "Overall, these findings suggest that exogenous IL-17B combined with IL-17RB contributes to the proliferation and migration of gastric cancers." (PMID 27146881, 2016). "To further confirm that the amplified IL-17RB functions in gastric cancer tissues need paracrine IL-17B, we depleted IL-17RB using its corresponding shRNA." (PMID 27146881, 2016). "To characterize the role of IL-17B/IL-17RB signaling on the stemness of gastric cancer, we performed real-time quantitative PCR to examine the expression of Oct4, Nanog, Lgr5, and Sall4 mRNA in MGC-803 cells treated with exogenous rIL-17B." (PMID 27146881, 2016). "Simultaneously, immunofluorescence staining indicated that the IL-17RB protein was predominantly expressed on the membrane of cancer cells, and that it was found in significantly higher levels in gastric cancer tissues." (PMID 27146881, 2016). "First, we examined the expression of IL-17RB in a panel of human gastric cancer cell lines (SGC-7901, MKN-45, BGC-823, MGC-803, and HGC-27) by western blotting and RT-PCR." (PMID 27146881, 2016). "To further confirm the role of IL-17B/IL-17RB signaling in gastric cancer, we performed colony forming assays and Transwell® assays using IL-17RB-depleted MGC-803 cells by adding exogenous recombinant human IL-17B (rIL-17B) protein." (PMID 27146881, 2016). "In the present study, we found, for the first time, that expression of IL-17RB was significantly increased in gastric cancer tissues, and patients with elevated IL-17RB expression had a worse prognosis." (PMID 27146881, 2016). "We have previously demonstrated that IL-17B/IL-17RB signal promoted progression of gastric cancer." (PMID 28145881, 2017). "We hypothesize that IL-17B/IL-17RB signaling enhances the stemness of gastric cancer by the AKT/β-catenin pathway." (PMID 27146881, 2016). "The results showed that IL-17RB was significantly increased in gastric cancer tissues." (PMID 27146881, 2016). "To further substantiate that IL-17B/IL-17RB signaling was essential in promoting upregulation of stemness-related genes in gastric cancer, we compared the protein expression by western blotting between IL-17RB-shRNA-MGC-803 cells and control cells treated with exogenous rIL-17B." (PMID 27146881, 2016).